TPM2 (tropomyosin 2)
Diseases named in the same sentence as TPM2 in open-access papers (continued):
Sharing a sentence is not in itself a finding about the gene and the disease.
atherosclerosis (6 papers, 2019 to 2023). A disease characterized by the build-up of fatty material and calcium deposition in the arterial wall resulting in partial or complete occlusion of the arterial lumen. "Studies have shown that TPM2 exhibited potential as a promising diagnostic and therapeutic biomarker for atherosclerosis." (PMID 34975513, 2021). "Through the cubic spline interpolation algorithm, we find the high-risk warning indicator of atherosclerosis intima-media thickness: 0.226 < TPM2 < 0.455, and 0.3 < expression of smooth muscle cell< 0.44." (PMID 31487691, 2019). "In summary, DEGs identified in the present study may assist clinicians in understanding the pathogenesis governing the occurrence and development of atherosclerosis, and TPM2 exhibits potential as a promising diagnostic and therapeutic biomarker for atherosclerosis." (PMID 31487691, 2019). "Univariate logistic regression showed that TPM2 (OR=0.150, 95% CI: 0.026-0.868, P=0.034) had clear correlations with atherosclerosis." (PMID 35371599, 2022). "In our previous research, tropomyosin 2 (TPM2) was reported as a potential predictive biomarker for atherosclerosis based on the screening of bioinformatics analysis and the verification of animal experiment." (PMID 35371599, 2022). "Western blotting analysis showed that the expression of α-SMA and TPM2 proteins was lower in the atherosclerosis group than in the normal group." (PMID 35371599, 2022). "The immunohistochemistry and immunofluorescence assays showed that the expression of TPM2 protein in the atherosclerosis group was lower than that in the normal group (P<0.05)." (PMID 35371599, 2022). "Following verification of animal model, the common DEG, Tropomyosin 2 (TPM2), was found, which were displayed at lower levels in the atherosclerosis models and samples." (PMID 31487691, 2019). "Then after comparing the bioinformatics result and proteomic data, Tropomyosin 2 (TPM2) was identified as a commonly differentially expressed gene, which exhibits potential as a molecular target or biomarker for atherosclerosis." (PMID 31487691, 2019). "A series of low flux experiments were subsequently performed to verify the role and function of TPM2 in atherosclerosis." (PMID 31487691, 2019). "The OR for atherosclerosis was 0.090 (95% CI, 0.028-0.293, p<0.001) in the group with high expression of TPM2 compared with low expression of TPM2." (PMID 31487691, 2019). "Results of RT-qPCR and western blotting analysis showed that the relative expression level of TPM2 was significantly lower in atherosclerosis samples, compared with the control groups (p<0.05)." (PMID 31487691, 2019). "The natural logarithmic atherosclerosis remained related to the TPM2 (β=-0.461 p<0.001) in the univariate linear regression model." (PMID 31487691, 2019). "And multicenter randomized controlled clinical trial should be performed, and recruit more subjects to verify the relationship between expression level of TPM2 and formation of atherosclerosis." (PMID 31487691, 2019). "Pearson correlation coefficient displayed that the status of atherosclerosis was significantly correlated with the expression of TPM2 (ρ=-0.567, p<0.001)." (PMID 31487691, 2019). "Bioinformatics analysis was applied to explore the potential role of TPM2 in atherosclerosis." (PMID 35371599, 2022). "Thus, during the development of atherosclerosis, the down-regulated expression of TPM2 leads to formation and movement disorders of VSMCs." (PMID 35371599, 2022). "TPM2 might be a potential novel atherosclerosis suppressor gene in vascular tissues, and it might represent a promising therapeutic gene target for atherosclerotic patients." (PMID 35371599, 2022). "TPM2 might be an independent protective factor for arteries, and one novel biomarker of atherosclerosis." (PMID 35371599, 2022). "It was further found that TPM2 may be a useful biomarker for the diagnosis and treatment of atherosclerosis." (PMID 35371599, 2022).
atherosclerosis (continued). "The expression of TPM2 was lower in atherosclerosis than normal artery (P<0.05)." (PMID 35371599, 2022). "Downregulation of TPM2 may lead to disorders in the formation and movement of VSMCs in the development of atherosclerosis." (PMID 34852854, 2021). "The receiver operator characteristic curve indicates that the expression level of TPM2 in our own experiment also could predict atherosclerosis sensitively and specifically (area under the curve for intimal thickness, 0.966; p<0.05)." (PMID 31487691, 2019). "This suggests that the low expression of TPM2 in the diseased arteries might damage the function of endothelial cells, and lead to the occurrence of atherosclerosis." (PMID 31487691, 2019). "The receiver operator characteristic curve indicates that the expression level of TPM2 in the GSE43292 could predict atherosclerosis sensitively and specifically (area under the curve for intimal thickness, 0.837; p<0.001)." (PMID 31487691, 2019). "This has culminated in the hypothesis that, in the development of atherosclerosis, the down-expression of TPM2 leads to disorders in the formation and movement of vascular smooth muscle cells." (PMID 31487691, 2019). "Secondly, we only conducted bioinformatics mining and animal experimental verification, which could demonstrate that TPM2 plays an important role in the occurrence and development of atherosclerosis to some extent." (PMID 31487691, 2019). "Therefore, we hypothesized that TPM2 may be related to cell proliferation and migration during the development of atherosclerosis." (PMID 35371599, 2022). "However, little research has investigated the expression of TPM2 in human atherosclerosis samples." (PMID 35371599, 2022). "However, no studies have yet confirmed whether the expression level of TPM2 in human AS tissues is lower than that of non-atherosclerosis tissues." (PMID 35371599, 2022). "The result demonstrated that TPM2 might be considered as biomarkers for atherosclerosis." (PMID 31487691, 2019). "Compared with the non-atherosclerotic tissues, the expression of TPM2 was down-regulated in the atherosclerosis samples." (PMID 35371599, 2022).
bladder cancer (6 papers, 2011 to 2025). "The high expression of TPM1 and TPM2 is associated with poor overall and disease-specific survival in patients with bladder cancer (P < 0.05)." (PMID 35734544, 2022). "The high expression of TPM1 and TPM2 is associated with poor overall and disease-specific survival in bladder cancer patients." (PMID 35734544, 2022). "The high expression of TPM1 and TPM2 was associated with poor overall and disease-specific survival in bladder cancer patients (P < 0.05)." (PMID 35734544, 2022). "The results showed that TPM1 and TPM2 were significantly upregulated in bladder cancer, with log2 fold-change values of +1.76 and +1.71, respectively, and adjusted p-values < 1E-13, indicating robust statistical support." (PMID 40937226, 2025). "We found that TPM1 and TPM2 were positively correlated with macrophage and NK cell infiltration in bladder cancer." (PMID 35734544, 2022). "The results showed that TPM1 and TPM2 were positively correlated with macrophage and NK cell infiltration in bladder cancer." (PMID 35734544, 2022). "TPM1 and TPM2 are positively correlated with the infiltration of macrophages and NK cells in bladder cancer." (PMID 35734544, 2022). "Univariate analysis showed that age, TPM1, and TPM2 were prognostic factors for bladder cancer (P < 0.05)." (PMID 35734544, 2022). "Therefore, TPM1 and TPM2 are effective markers for the diagnosis of bladder cancer and are expected to be potential therapeutic targets for bladder cancer." (PMID 37686101, 2023). "It has been reported that TPM1 and TPM2 are highly expressed in normal urothelial tissues, but the expression of TPM1 and TPM2 is decreased in the early stage of bladder cancer, which may be a marker event of the occurrence and development of bladder cancer." (PMID 35734544, 2022). "In conclusion, TPM1 and TPM2 are effective markers for the diagnosis of bladder cancer." (PMID 35734544, 2022). "TPM1 and TPM2 are effective markers for the diagnosis of bladder cancer." (PMID 35734544, 2022). "The expression levels of TPM1, TPM2, TPM3, and TPM4 in low grade bladder cancer were lower than those in high grade bladder cancer (P < 0.05)." (PMID 35734544, 2022). "The expression levels of TPM1, TPM2, TPM3, and TPM4 in low-grade bladder cancer were lower than those in high-grade bladder cancer." (PMID 35734544, 2022). "The existing literature provides evidence that TPM1, TPM2, and TPM3 mRNA expression is altered in bladder cancer tissues and may be correlated with adverse clinical outcomes." (PMID 40937226, 2025). "The expression levels of TPM1, TPM2, and TPM4 genes were decreased in bladder cancer cells." (PMID 37686101, 2023). "In addition, ROC curve indicated that TPM1, TPM2, and TPM3 had significant accuracy in the diagnosis of bladder cancer." (PMID 35734544, 2022). "Our study showed that TPM1, TPM2, and TPM4 were underexpressed in bladder cancer tissues." (PMID 35734544, 2022). "We have previously observed that TPM1, TPM2, and TPM4 are low expressed in bladder cancer, and therefore, the infiltration of NK cell, macrophages, neutrophils, and Th1 may be reduced accordingly in bladder cancer." (PMID 35734544, 2022). "Therefore, TPM1, TPM2, and TPM3 are expected to be new markers for the diagnosis of bladder cancer and will play a potentially great value in clinical conversion application." (PMID 35734544, 2022). "Therefore, we infer that the low expression of TPM1, TPM2, and TPM4 is a mechanism of immunosuppression in bladder cancer." (PMID 35734544, 2022). "Therefore, the low expression of TPM1, TPM2, and TPM4 in the tumor tissues of bladder cancer may be beneficial to the rapid proliferation of bladder cancer cells, indicating the development of bladder cancer." (PMID 35734544, 2022).
bladder cancer (continued). "It is worth noting that although TPM1 and TPM2 are highly expressed in normal urothelial tissues, the expression of TPM1 and TPM2 is decreased in the early stage of bladder cancer, which may be a marker event for the occurrence and development of bladder cancer." (PMID 37686101, 2023).
colon cancer (6 papers, 2017 to 2024). "Through bioinformatics analysis, TPM2, as one of the six immune-related genes, is significantly associated with the prognosis of colon cancer and constitutes an immune-related prognosis model of colon cancer, which plays a key role in the tumor immune microenvironment." (PMID 37686101, 2023). "Only eight genes (UCN, TRIM, RBCK1, TPM2, CD36, NMB, PPARGC1A, and LGALS4) significantly affected the OS in patients with colon cancer (P < 0.05)." (PMID 35572595, 2022). "In conclusion, our data strongly support the notion of a key role of TASCs in colon cancer clinical course and identify TPM2 and CNN1 as novel and robust prognostic markers for colon cancer prognostication." (PMID 35454931, 2022). "In our study, based on the colon cancer immune gene datasets, we used WGCNA to identify 21 immune-related hub genes affecting patients’ OS and constructed IRGPI based on 8 independent OS prognostic factors (UCN, TRIM58, RBCK1, TPM2, CD36, NMB, PPARGC1A, and LGALS4)." (PMID 35572595, 2022). "In addition, considering the functional specificities of CNN1 and TPM2 proteins, our data suggests that TASC biomechanical properties might be of relevance for colon cancer progression." (PMID 35454931, 2022).
hypertrophic cardiomyopathy (5 papers, 2016 to 2024). A condition in which the myocardium is hypertrophied without an obvious cause. "For example, various TPM1 and TPM2 mutations have been implicated in hypertrophic cardiomyopathy (HCM) including familial hypertrophic cardiomyopathy (FHC) in humans." (PMID 27703814, 2016). "TPM2 is the major myosin isoform in skeletal muscle and was enriched in the hypertrophic cardiomyopathy (HCM) signaling pathway in this study." (PMID 39634756, 2024). "In the cases of dilated cardiomyopathy, cardiac muscle contraction, and hypertrophic cardiomyopathy (B), seven downregulated proteins were enriched, including Myl2, Myl3, Myh7, Atp2a1, Tpm1, Tpm2, and Ttn." (PMID 39861068, 2024). "Due to the relatively low number of detected down-regulated genes, only one pathway was found to be significant, and it contained genes overexpressed at the start of the training schedule (T1): hypertrophic cardiomyopathy (HCM) pathway (CACNB1, TPM1, TPM2, TTN)." (PMID 28381206, 2017).
cap myopathy (4 papers, 2017 to 2025). Cap myopathy is a very rare congenital myopathy presenting a weakness of facial and respiratory muscles associated with craniofacial and thoracic deformities, as well as weakness of limb proximal and distal muscles. "Deletion of Glu139 in β-tropomyosin caused by a point mutation in TPM2 gene is associated with cap myopathy characterized by high myofilament Ca2+-sensitivity and muscle weakness." (PMID 29196649, 2017).
dilated cardiomyopathy (4 papers, 2022 to 2025). Cardiomyopathy which is characterized by dilation and contractile dysfunction of the left and right ventricles. "Necroptosis, neutrophil extracellular trap formation, cardiac muscle contraction, and dilated cardiomyopathy, among others, are some pathways affected by downregulated proteins such as Pgam5, Slc25a4, and H2ax as well as Myl2, Myl3, Atp2a1, and Tpm2." (PMID 41011134, 2025).
cardiomyopathy (3 papers, 2016 to 2026). A disease of the heart muscle or myocardium proper. "It is worth noting that the combination of the heterozygous variants in CAP2, ADCY6, and SYNE2, associated with the loss of function in TPM2, could also be related to cardiomyopathy." (PMID 37744435, 2023).
cataract (3 papers, 2018 to 2023). Partial or complete opacity of the crystalline lens of one or both eyes that decreases visual acuity and eventually results in blindness. "One study showed that Tpm2 knockout mice had an earlier onset and faster progression of cataracts, and that the opacities first appeared in the centre of the anterior cortex." (PMID 37118843, 2023). "Moreover, we have reported that the expression of Tpm1 and Tpm2 was induced/elevated in the HLECs of human cataracts with ASF, or so-called anterior subcapsular cataracts, and in human PCO tissues surgically removed from patients affected by non-traumatic dislocated intraocular lens (IOL)." (PMID 30304871, 2018). "In our previous study, Tpm1 and Tpm2 were upregulated in the multilayered, spindle-shaped LECs in a rat model of PCO, human cataracts with anterior subcapsular fibrosis, and human differentiated LECs in a dislocated lens capsule." (PMID 33918979, 2021). "We assessed the expression of isoforms from the Tpm1 and Tpm2 genes in a mouse and a rat model of PCO in vivo, and in LECs obtained from human subjects of various ages with cataracts." (PMID 30304871, 2018).
Skeletal myopathy (3 papers, 2017 to 2023). "Inhibition of Smad4 SUMOylation impaired spatial learning and memory in rats by downregulating TPM2, a gene associated with skeletal myopathies." (PMID 29183317, 2017). "Among the TPM2 mutations associated with skeletal myopathies, the TPM2E122K mutation was found to reduce TPM2 expression and impair spatial learning and memory in rats." (PMID 29183317, 2017). "Several TPM2 mutations were found to be associated with skeletal myopathies." (PMID 29183317, 2017).
acute liver failure (2 papers, 2020 to 2023). Rapid deterioration of liver function causing encephalopathy and coagulopathy. "Several transcriptomic analyses have demonstrated that TPM2 expression is increased approximately 4- to more than 6-fold in HBV-associated HCC or acute liver failure, respectively." (PMID 33553000, 2020). "Studies have found that overexpression of TPM2 increases the production of HBV, and in HBV-related HCC or acute liver failure, TPM2 expression increases about 4-fold to over 6-fold, respectively." (PMID 37686101, 2023).
Arrhythmia (2 papers, 2013 to 2017). Any cardiac rhythm other than the normal sinus rhythm. "Four proteins (GJA1, TPM2, GJA5 and C1QBP) were related with cardiac arrhythmias, cardiac dysfunction and cardiac cell damage, and might also be responsible for DCM." (PMID 23940716, 2013).
cervical carcinoma (2 papers, 2009 to 2013). A carcinoma arising from either the exocervical squamous epithelium or the endocervical glandular epithelium. "In both vaginal and cervical carcinoma there was a downregulation of vimentin, filamin, tropomyosin 2 (TM2 beta) as well as vinculin." (PMID 19367286, 2009). "Of the 17 downregulated proteins, 6 different proteins showed low expression in both vaginal and cervical carcinoma compared with normal vaginal tissue (calreticulin, tropomyosin 2 beta, vimentin, gelsolin, vinculin and filamin)." (PMID 19367286, 2009).
clubfoot (2 papers, 2022 to 2024). The most common congenital deformation of the foot, occurring in 1 of 1,000 live births. "The number of TPM2 variants with uncertain significance is likely to increase because these variants are being identified in patients with isolated clubfoot, which is much more common than myopathies or arthrogryposes." (PMID 35579956, 2022). "One approach toward understanding isolated clubfoot is to expand clinical sequencing, which will likely uncover novel TPM2 variants." (PMID 35579956, 2022). "Considering the advantages of zebrafish as a system, our transient overexpression assay could be further used to uncover new pathogenic variants of TPM2 and to test additional genes of uncertain significance that contribute to the pathology of isolated clubfoot or other musculoskeletal disorders." (PMID 35579956, 2022). "Initially, genes associatedwith clubfoot (PITX1, TBX4, HOXA9, HOXD10, HOXD12,HOXD13, HOXA9, TPM1, TPM2, COL9A1, FLNB, CASP8,CASP10, UTX, CHD1, RIPPLY2, CAND2, WNT7) werescreened for potential variants." (PMID 38952703, 2024).
endometriosis (2 papers, 2019 to 2024). The growth of functional endometrial tissue in anatomic sites outside the uterine body. "Expression of TPM2 was higher in ectopic versus eutopic tissue and increased in secretory phase eutopic tissue from endometriosis patients compared to both control groups." (PMID 30992697, 2019). "Similarly, expression of two proteoforms of TPM2 was higher in ectopic versus eutopic tissue and in secretory phase endometriosis compared to control groups [e.g. spot 1548 (EcS/ES = 4.15, P = 0.0002; ES/CS = 3.15, P < 0.0001; ES/PS = 2.36, P = 0.0057)]." (PMID 30992697, 2019). "From the tissue profiling, TNC, CPM, TPM2, LUM and PAEP were selected for further testing as serological markers using samples from 87 women (control n = 21; pain control n = 21; endometriosis n = 45)." (PMID 30992697, 2019).
Escobar syndrome (2 papers, 2021 to 2022). "While CHRNG mutations caused Escobar syndrome for 75 patients of known cases, a number of patients had a genetic etiology associated with variants in the TPM2, CHRND, CHRNA1, MUSK, MYH3, RAPSN, and DOK7 genes." (PMID 36292632, 2022). "Mutations in the TPM2 gene could explain some symptoms of Escobar syndrome such as distal arthrogryposis, psychomotor delay, and reduced muscle bulk observed in distal arthrogryposis." (PMID 36292632, 2022). "Only three papers described mutations in the TPM2 gene associated with Escobar syndrome." (PMID 36292632, 2022). "Indeed, mutations in CHRNA1, CHRND, and TPM2 have been described to be associated with Escobar syndrome." (PMID 36292632, 2022). "To date, 83 patients with Escobar syndrome with mutations in CHRNG and TPM2 have been reported in the literature." (PMID 36292632, 2022).